ADK (adenosine kinase)
Diseases named in the same sentence as ADK in open-access papers (continued):
Sharing a sentence is not in itself a finding about the gene and the disease.
breast carcinoma (12 papers, 2005 to 2025). "In view of the present results, obtained in the female Sprague–Dawley rat, it can be envisaged that the long-term inhibition of mammary ADK promotion by a brief, preventive treatment with melatonin could also reduce the risk of breast cancer induced in women by unidentified environmental factors." (PMID 15987452, 2005). "Dysregulation of ADK isoforms, particularly overexpression of the nuclear long isoform (ADK-L), has been observed in breast cancers, contributing to tumor growth and metastasis." (PMID 41048997, 2025). "Since ADK appears necessary for increases of both AMPK activity and p62 by AICAr in NRVMs, we compared ADK expression in NRVMs, mouse hearts and the breast cancer cell line, MCF7." (PMID 41231272, 2025). "Selective knockout of ADK isoforms via CRISPR/Cas9-mediated approaches suppressed breast cancer cell migration and invasion, which with the elevation of a tumor-related enzyme, matrix metalloproteinases, and downregulation of cyclin D2 and THB1." (PMID 35721189, 2022). "The expression of ADK was shown to be upregulated in specific cancer types, including colorectal cancer, and breast cancer." (PMID 35721189, 2022). "Adenosine signaling is associated with breast carcinoma and it is identified that downregulation of ADK decreases proliferation, migration, and invasion of TNBC cells, suggesting a functional role of ADK in TNBC50." (PMID 34711841, 2021). "Through proteomic profiling, we discovered a metabolic signature comprised of TALDO1, GPI, LDHA, SHMT2, and ADK proteins that were downregulated in Trop2-depleted breast cancer tumors." (PMID 34711841, 2021). "Using our established CRISPR/Cas9 approach of targeting the start codon of each ADK isoform, we further evaluated the effect of ADK-L or ADK-S knockdown in MDA-MB-231 breast cancer cell line on cell proliferation and viability." (PMID 31921385, 2019). "To further evaluate the role of ADK isoforms in breast cancer cellular pathology, we established an in vitro model with CRISPR/Cas9 mediated manipulation of ADK in breast cancer." (PMID 31921385, 2019). "In this present study, we explored expression profiles of ADK isoforms in tumor tissues of 46 breast cancer patients and breast cancer cell lines." (PMID 31921385, 2019). "To further explore the profile of ADK isoforms in breast cancer, we have investigated the ADK expression profiles in several established breast cancer cell lines, including MDA-MB-231, and MCF7." (PMID 31921385, 2019). "Therefore, in this study, we first characterized the expression profiles of ADK isoforms in different types of breast cancer." (PMID 31921385, 2019). "Therefore, while we provide promising findings from the manipulation of ADK isoforms in cellular behaviors of cancer cells, it is still premature to draw any firm conclusions regarding ADK isoforms as a specific biomarker in breast cancer." (PMID 31921385, 2019). "We hypothesized that these two ADK isoforms would be differentially expressed in breast cancer and may contribute to divergent cellular actions in cancer." (PMID 31921385, 2019). "Furthermore, we established a CRISPR/Cas9 system to selectively modify each ADK isoform in cultured MDA-MB-231 breast cancer cells and scrutinized the contributions of different ADK isoforms on cancer cell pathology." (PMID 31921385, 2019). "This raises the possibility that differences in ADK expression between the heart and breast cancer cells might be exploited by pretreating with AICAr or similar drugs to selectively protect cardiomyocytes against doxorubicin toxicity while enhancing its chemotherapeutic efficacy in tumors." (PMID 41231272, 2025). "However, the role of the two different isoforms of ADK in tumorigenesis, and specifically with the progression of breast cancer, remains unclear." (PMID 31921385, 2019).
breast carcinoma (continued). "To investigate the profile of ADK isoforms in breast cancer, we compared the expression levels of ADK-L and ADK-S in cancer tissues versus NAT controls in patients with breast cancer (n=46)." (PMID 31921385, 2019). "Importantly, MCF7 breast cancer cells, which poorly express ADK, were not protected by AICAr pretreatment and instead were sensitized to doxorubicin-induced cell death." (PMID 41231272, 2025). "Transcript levels of five of the seven metabolic genes (TALDO1, GPI, SHMT2, LDHA, and ADK: 5-gene metabolic signature) and six oncogenes: TAGLN2, NOLC1, HSP90AB1, HDGF, MCM5, and NCL, were elevated in TNBC patients when compared to patients with ER+ breast cancer." (PMID 34711841, 2021). "Transient autophagy inhibition by AICAr and accumulation of p62 depends upon ADK activity, so that MCF7 breast cancer cells, which poorly express ADK, are not protected by AICAr." (PMID 41231272, 2025).
diabetes (8 papers, 2011 to 2020). "Further studies developing a specific delivery strategy to selectively inhibit ADK in pancreatic β cells using an ADK inhibitor have important value for treating diabetes." (PMID 31044530, 2019). "The increase of adenosine level with decrease in adenosine kinase in diabetes results in deamination of adenosine and the increase in adenosine deaminase." (PMID 28050278, 2016). "Adenosine deaminase and adenosine kinase expression and protein levels showed a significant decrease in diabetic retinas 30 days after diabetes induction." (PMID 23840723, 2013). "In diabetes, the suppressed proliferation potential of diabetic T lymphocytes with mitogen stimulated was achieved by a decreased expression of adenosine kinase, and decreased IL-2 production by mitogen-stimulated diabetic T cells has been reported." (PMID 21716679, 2011). "Taken together, both recent studies and our studies using cell‐type‐specific genetic knockout models of ADK have provided strong evidence that targeted inhibition of pancreatic β‐cell ADK could be a useful strategy for the treatment of diabetes." (PMID 31044530, 2019). "Accordingly, in this study we evaluated the effect diabetes/hyperglycemia, considered the main cause of diabetes complications, have on the expression and protein levels of adenosine receptors and of the enzymes adenosine deaminase (ADA) and adenosine kinase (AK)." (PMID 23840723, 2013).
schizophrenia (6 papers, 2020 to 2024). A major psychotic disorder characterized by abnormalities in the perception or expression of reality. "A transgenic mouse model of ADK overexpression resulted in an extracellular adenosine deficiency in the brain as well as cognitive and locomotor deficits that model schizophrenia-like endophenotypes." (PMID 39404420, 2024). "These consistent null findings of ADK expression in the schizophrenic brain suggest that an elevation of ADK protein expression is not a likely cause of the proposed adenosine hypofunction in schizophrenia." (PMID 36998267, 2023). "The mRNA expression of ADK was significantly greater in males than in females in schizophrenia and control subjects combined as well as in schizophrenia subjects alone, but not in control subjects alone, suggesting a disease effect." (PMID 39404420, 2024). "Of the six transcripts, ADK mRNA expression was significantly higher in male compared with female schizophrenia and control subjects combined (Mann–Whitney U = 86; p = 0.014)." (PMID 39404420, 2024). "If anything, a rare case with a copy number variant of the ADK gene has been discovered in a cohort of 1,699 schizophrenia patients, who had extremely low ADK levels in the blood." (PMID 36998267, 2023). "In an animal model of transgenic mice that overexpress adenosine kinase, researchers observed the development of cognitive and locomotor impairments similar to those found in schizophrenia." (PMID 35163142, 2022). "While ADK expression appears largely unaffected in schizophrenia, there is evidence that other metabolic regulators of adenosine might be affected with consequential reduction in ambient adenosine levels in the brain." (PMID 36998267, 2023). "Although it has been proposed that increased expression of the enzyme adenosine kinase may drive adenosine hypofunction, recent findings show no significant changes in adenosine kinase expression in the brain in schizophrenia." (PMID 36233136, 2022). "Furthermore, genes (including GRM1, ADK, CACNA1C, CRK and GAB1) which the most significant SNPs of the five first-generation antipsychotics specific analyses are located within were both associated with the schizophrenia and heart diseases." (PMID 35136033, 2022). "hypothesized that increased adenosine kinase activity in astrocytes may reduce extracellular adenosine, with subsequent hypofunction on the adenosine neurotransmitter system, which is altered in schizophrenia." (PMID 32733292, 2020). "In animal models of schizophrenia-like behaviors, augmenting adenosine levels in mice that overexpress the enzyme ADK and antagonism of the P2X7R in the sub-chronic phencyclidine-induced model of schizophrenia, significantly improved cognitive deficits." (PMID 36233136, 2022). "ADK mRNA expression was not significantly different between schizophrenia and control subjects in dorsolateral prefrontal cortex (DLPFC) tissue, a finding that extended to the cell-level investigation in astrocytes and pyramidal neurons in the same study." (PMID 39404420, 2024). "Likewise, ADK mRNA expression in peripheral blood showed no alteration in patients with schizophrenia." (PMID 36998267, 2023). "Finally, in silico analysis of post-mortem expression of ADK using microarray and RNAseq databases, did not identify any abnormalities of ADK expression in frontal cortices in people with schizophrenia." (PMID 36998267, 2023). "On the contrary, a later paper showed that the lower extracellular adenosine levels, which are posited to be partly responsible for glutamatergic and dopaminergic system dysregulation and schizophrenia manifestations, seem not to be related to adenosine kinase overexpression." (PMID 35163142, 2022). "In an enriched population of ACC pyramidal neurons, the mRNA expression levels of ADK, ENT1, ENT2, ENTPD1, ENTPD3, and NT5E were assessed between individuals with schizophrenia and sex- and age-matched non-psychiatrically ill control subjects." (PMID 39404420, 2024).
schizophrenia (continued). "Elevated ADK levels suggest enhanced intracellular substrate availability, but the lack of significantly elevated ENT1 mRNA levels in schizophrenia subjects could mean that adenosine transport may not be markedly altered." (PMID 39404420, 2024). "In the present study, we assayed the transcript expressions of ADK, ENT1, ENT2, ENTPD1, ENTPD3, and NT5E in an enriched population of pyramidal neurons in the postmortem ACC tissue of patients diagnosed with schizophrenia compared with non-psychiatrically ill sex- and age-matched patients." (PMID 39404420, 2024).
Stroke (6 papers, 2013 to 2021). Sudden impairment of blood flow to a part of the brain due to occlusion or rupture of an artery to the brain. "Here, we describe two patients with ADK deficiency and vascular tortuosity leading to stroke in one of them." (PMID 34765398, 2021). "ADK deficiency is a rare inborn error of methionine metabolism with a complex phenotype that might be associated with cerebrovascular abnormalities and stroke." (PMID 34765398, 2021). "Adenosine kinase (ADK) can inhibit the expression of adenosine, and under-expression of cerebral ADK in transgenic mice can induce cortical protection, suggesting a promising target for developing a stroke therapy." (PMID 33071923, 2020).
colorectal cancer (5 papers, 2019 to 2023). A primary or metastatic malignant neoplasm that affects the colon or rectum. "In the same context, work on colorectal cancer has demonstrated the presence of other activating mutation as the D842V in the exon 18 in 2 of 322 ADK cases." (PMID 33213472, 2020). "The available data suggests that there is a potential rolefor ADK in the development of colorectal cancer (CRC), as well as breast and liver cancer." (PMID 37538807, 2023). "The inhibition of ADK activity by specific inhibitors significantly prevents the occurrence of inflammation, and promotes the growth of liver cancer cells, whereas the activation of ADK expression promotes the growth of colorectal cancer cells." (PMID 31370143, 2019). "Thus, it was shown that the tumor tissue of patients with colorectal cancer had an elevated level of ADK gene expression and ADK activity in comparison with healthy tissue." (PMID 35327609, 2022).
COVID-19 (5 papers, 2020 to 2023). A disease caused by infection with severe acute respiratory syndrome coronavirus 2. "ADK inhibitors are potent anti-inflammatory agents, they may also be of therapeutic benefit in septic shock caused by COVID-19." (PMID 33324223, 2020). "It is likely that tissue hypoxia and inflammation in COVID-19 leads to decrease in the expression of the adenosine transporters and ADK, in addition to increases in intracellular and extracellular levels of adenosine." (PMID 34372575, 2021). "Among them, six (ADK, DHFR, METAP2, PIN4, SC5D, and TMEM263) had matching risk factor genes showing consistent patterns, i.e., transcriptional downregulations increased the COVID-19 mortality risk." (PMID 35547187, 2022). "Adenosine and the key adenosine regulators adenosine deaminase (ADA), adenosine kinase (ADK), and equilibrative nucleoside transporter 1 may play a role in COVID-19 pathogenesis." (PMID 33324223, 2020). "Depending on the stage of exposure to and infection by SARS-CoV-2, enhancing adenosine levels by targeting key adenosine regulators such as ADA, ADK and equilibrative nucleoside transporter 1 might find therapeutic use against COVID-19 and warrants further investigation." (PMID 33324223, 2020). "This raises the possibility of targeting ADA and ADK for prevention and/or treatment of ARDS during later phases of COVID-19." (PMID 33324223, 2020). "The enzymatic roles of ADK and ADA might be targeted to ameliorate ARDS that often is present in patients with severe COVID-19." (PMID 33324223, 2020).
temporal lobe epilepsy (5 papers, 2020 to 2024). A localization-related (focal) form of epilepsy characterized by recurrent seizures that arise from foci within the temporal lobe, most commonly from its mesial aspect. "The disrupted adenosinergic system, e.g., altered densities of A1R, A2AR, and the adenosine metabolic enzyme, adenosine kinase (ADK) were also seen in different brain areas in patients with temporal lobe epilepsy (TLE) and correlated to SUDEP risk." (PMID 35754505, 2022). "The overexpression of the adenosine kinase (ADK) and adenosine deaminase (ADA) genes was found to be associated with neuronal hyperexcitability and seizure activity in temporal lobe epilepsy." (PMID 38641945, 2024). "ADK overexpression as a general response to astroglial activation is considered a neuropathological feature of temporal lobe epilepsy, focal cortical dysplasia, and contribute to the epileptogenic process itself." (PMID 37583518, 2023).
cognitive deficits (4 papers, 2016 to 2023). "In addition, ADK expression changes in the adult brain are also associated with various cognitive deficits." (PMID 35893077, 2022). "Homozygous deletion of the ADK gene in mice resulted in the development of seizures and cognitive deficits." (PMID 36589157, 2022).
glioma (4 papers, 2018 to 2022). A benign or malignant brain and spinal cord tumor that arises from glial cells (astrocytes, oligodendrocytes, ependymal cells). "Most recently, it has been found that a significantly enhanced expression of ADK in specimens of patients with glioma, both the tumor center and peritumoral tissue." (PMID 35721189, 2022). "ADA and ADK are upregulated in higher grade gliomas but the relevance for tumor progression requires further research." (PMID 30441833, 2018). "ADK was detected in the cytoplasm as well as in the nuclei of cells obtained from gliomas." (PMID 30441833, 2018). "ADA and ADK levels were upregulated in patients with Grade II and Grade III gliomas compared to control subjects." (PMID 30441833, 2018). "ADK and ADA, by regulating adenosine concentration, might also play a role in tumor growth and apoptotic cell death in gliomas, modulating proliferation of glial and endothelial cells." (PMID 30441833, 2018). "Recent evidence indicates that ADK and ADA levels are related to glioma progression." (PMID 30441833, 2018).
liver cancer (4 papers, 2019 to 2025). An epithelial or non-epithelial malignant neoplasm that arises from the liver. "In addition, lower ADK expression was linked to liver cancer relapse." (PMID 37999212, 2023). "Besides, decreased expression of ADK was associated with liver cancer relapse." (PMID 35327609, 2022). "On the contrary, patients with liver cancer had decreased levels of ADK in tumor tissue in comparison with healthy tissue." (PMID 35327609, 2022). "However, the exact mechanism and the abnormal expression patterns of key genes involved in adenosine metabolism, namely adenosine kinase (ADK) and equilibrative nucleoside transporter type 4 (ENT4), in clinical liver cancer cases have been recently reported." (PMID 39546272, 2025).
astrocytoma (3 papers, 2018 to 2023). "A lentivirus vector carrying anti-ADK miR-shRNA abolished ADK expression at a 95% capacity in Wharton's jelly mesenchymal stem cells (hWJMSCs) and the astrocytoma cell line." (PMID 33815100, 2021). "By developing this system, we succeeded todiminish ADK expression up to 95% in astrocytoma cellline and in WJMSCs." (PMID 29308612, 2018). "In order toscreen and select the most efficient anti-ADK miR-shRNA,astrocytoma cell line was employed." (PMID 29308612, 2018). "In this study, we describe an efficient approach for stable knockdown of adenosine kinase (ADK) using lentiviralsystem, in an astrocytoma cell line and in human Wharton’s jelly mesenchymal stem cells (hWJMSCs)." (PMID 29308612, 2018). "However, in the other group, TCGA astrocytoma, A2AR was negatively linked to HIF1, ENPP1, and pannexin, and positively correlated to ADK." (PMID 37047660, 2023). "However, in the other group, TCGA astrocytoma, A2AR was negatively related to HIF1a, ENPP1 (ectonucleotide pyrophosphatase/phosphodiesterase 1), and pannexin, and positively correlated with ADK (adenosine kinase)." (PMID 37047660, 2023).
Hepatic steatosis (3 papers, 2013 to 2022). Steatosis is a term used to denote lipid accumulation within hepatocytes. "Histologically, hepatic steatosis, fibrosis, and cirrhosis were described in ADK-deficient patients." (PMID 36589157, 2022). "However, it is noted that the systemic application of ADK inhibitors can be associated with a number of adverse reaction, including a decrease of cardiovascular functions and the development of hepatic steatosis." (PMID 33390891, 2020). "ADK is an enzyme involved in liver metabolism and its deficiency may lead to the development of hepatic steatosis." (PMID 24206787, 2013).